STAT3 (signal transducer and activator of transcription 3)
Diseases named in the same sentence as STAT3 in open-access papers (continued):
Sharing a sentence is not in itself a finding about the gene and the disease.
myxoma (1 paper, 2024). A benign soft tissue neoplasm characterized by the presence of spindle and stellate cells, lobulated growth pattern, and myxoid stroma formation. "To further confirm the role of STAT3 in the secretion of IL-6, we transfected antibody-free myxoma cells with STAT3 siRNA." (PMID 38396907, 2024). "The present study also demonstrated that STAT3 was constitutively phosphorylated together with spontaneous secretion of IL-6 in the cultured myxoma cells." (PMID 38396907, 2024). "The immunofluorescence signal of phosphorylated STAT3 located in the nuclei of the myxoma cells after incubation with IL-6 + sIL-6R for 30 min was compared with the untreated control cells." (PMID 38396907, 2024). "Transfection of STAT3 significantly attenuated spontaneous IL-6 secretion from the myxoma cells compared with control-scrambled siRNA transfection." (PMID 38396907, 2024). "Thus, we analyzed trans-signaling by using IL-6 + sIL-6R for activation of IL-6 mRNA and found that IL-6 trans-signaling caused autocrine activation of IL-6 gene expression through STAT3 and PI3K/Akt pathways in the myxoma cells." (PMID 38396907, 2024). "We next examined whether the culture supernatant derived from the myxoma cells have transferrable biologic properties to stimulate STAT3 phosphorylation in cultured HUVECs." (PMID 38396907, 2024). "The secretion of IL-6 from the myxoma cells was significantly inhibited by the treatment with AG490 (JAK2 inhibitor, 100 μmol/L), piceatannol (STAT1/3 inhibitor, 100 μmol/L), LLL12 (STAT3 inhibitor, 10 μmol/L), and Ly294002 (PI3K/Akt inhibitor, 30 μmol/L)." (PMID 38396907, 2024). "In the present study, stimulation with IL-6 + sIL-6R resulted in an increase in IL-6 mRNA, and pharmacological inhibitors against JAK/STAT3 and PI3L/Akt inhibited the IL-6 + sIL-6R-induced activation of IL-6 mRNA in the myxoma cells." (PMID 38396907, 2024).
neuroendocrine tumor (1 paper, 2022). "In neuroendocrine tumor cells, the signal transducer and activator of the transcription 3 (STAT3)/IL-6 axis has been implicated in proliferation, survival, and differentiation through MAPK-dependent signaling." (PMID 36294509, 2022).
neuroepithelial tumors (1 paper, 2020). "The first subgroup revealed transcriptional activation of STAT3 and TGF-signaling pathways and contained predominantly dysembryoplastic neuroepithelial tumors (DNTs)." (PMID 31919458, 2020).
neurofibromatosis-2 (1 paper, 2014). "On the other hand, there are reports that indicate involvement of Let-7a with constitutively active and phosphorylated STAT3 through NF-2 (neurofibromatosis-2)." (PMID 25539644, 2014).
nodular medulloblastomas (1 paper, 2016). "It was found that nuclear translocation of p-STAT3 could be observed in 63.9% (39/61) of the classical, 81.8% (36/44) of the large-cell, 53.3% (8/15) of the nodular medulloblastomas and 23.5% (4/17) of tumor-surrounding brain tissues." (PMID 28035977, 2016).
non-melanoma skin carcinoma (1 paper, 2019). "The studies concerning expression of STAT3 in non-melanoma skin cancer (NMSC), although scarce, also have shown increased expression of these proteins in NMSC cells compared to normal epidermis." (PMID 31342143, 2019).
Noonan syndrome (1 paper, 2017). Noonan Syndrome (NS) is characterized by short stature, typical facial dysmorphism and congenital heart defects. "Stat3 was aberrantly suppressed in peripheral blood cells from Noonan syndrome patients with gain-of-function Shp2 mutations, while Stat3 activation was significantly attenuated by activated Shp2 in bone marrow cells." (PMID 28085101, 2017).
odontogenic tumours (1 paper, 2020). "In summary, the analyses of odontogenic tumours and non-tumoural samples by immunohistochemistry and western blotting indicated activation of the NF-κB, AKT, STAT3 and WNT/β-catenin pathways in tumoural samples, independent of their genetic background." (PMID 31900382, 2020).
oral candidiasis (1 paper, 2023). Infection of the mucosal lining of the mouth with the fungus Candida albicans. "ilicifoliusmethanol extract increased STAT3 expression and decreased tongue epithelial cell death caused by oral candidiasis." (PMID 36764307, 2023). "Further study was needed to investigate the correlation between the invasion of candida albicans, STAT3 expression, Th-17/IL-17, and the amount of epithelial cell death in oral candidiasis immunosuppressed rats to determine the severity of the disease." (PMID 36764307, 2023). "ilicifoliusmethanolic extract leads to increased STAT3 expression and decreased tongue epithelial cell death in oral candidiasis under immunosuppressive conditions and that this effect is similar to that of nystatin." (PMID 36764307, 2023). "ilicifoliustherapy on oral candidiasis under immunosuppressed conditions, with the aim of understanding the action of the herbal extract through the STAT3 pathway, which is one of the body's defense lines against fungal invasion." (PMID 36764307, 2023). "STAT3 expression significantly increased in the nystatin-treated group compared with the immunosuppressed control group and the immunosuppressed group with oral candidiasis." (PMID 36764307, 2023).
Oral ulcer (1 paper, 2023). Erosion of the mucous mebrane of the mouth with local excavation of the surface, resulting from the sloughing of inflammatory necrotic tissue. "Additionally, IL-6 mRNA was upregulated in the oral ulcer region, suggesting increased Hamp and hepcidin levels via the IL-6/STAT3 pathway owing to inflammation in the OUM model." (PMID 37079608, 2023).
oropharyngeal cancer (1 paper, 2025). Carcinoma, predominantly squamous cell, arising from the epithelial cells of the oropharynx. "It is confirmed that Stat3 can bind GPX4 promoter region, then regulate GPX4 protein expression in oropharyngeal cancer cell by chromatin immunoprecipitation assay." (PMID 41341590, 2025).
osteomyelitis (1 paper, 2023). An acute or chronic inflammation of the bone and its structures due to infection with pyogenic bacteria. "We further found that 3 TFs, including CRBPB, ETS2, and STAT3 were highly expressed in both osteomyelitis and DFU." (PMID 37904457, 2023). "Upon further validation, we identified 3 TFs highly expressed in osteomyelitis and DFU, including CRBPB, ETS2, and STAT3." (PMID 37904457, 2023).
ovarian disease (1 paper, 2019). "Epidermal Growth Factor Receptor (EGFR) is, for the most part, deregulated and over-communicated in ovarian disease, which islegitimately connected with STAT3 enactment that prompts the collection of hostile to apoptotic occasions and along these lines, docetaxelmedicate obstruction happens." (PMID 31285646, 2019).
pancreatic neuroendocrine tumor (1 paper, 2022). Pancreatic endocrine tumor, also known as pancreatic neuroendocrine tumor (PNET), describes a group of endocrine tumors originating in the pancreas that are usually indolent and benign, but may have the potential to be malignant. "Related studies suggest that NRP-1 may be regulated by STAT3, and that NRP-1 is upregulated in pancreatic neuroendocrine tumor tissues and correlates with the metastatic ability of pancreatic neuroendocrine tumor cells." (PMID 36105933, 2022).
pelvic inflammatory disease (1 paper, 2024). Pelvic inflammatory disease (PID) is an acute or chronic inflammation in the pelvic cavity. "The mechanism by which modified Hongteng Baijiang decoction improves endometrial receptivity in sequelae of pelvic inflammatory disease rats may be related to the LIF/JAK2/STAT3 signaling pathway and gut microbiota." (PMID 38896093, 2024).
pemphigus (1 paper, 2019). Pemphigus is a group of rare autoimmune diseases that cause blistering of the skin and mucous membranes (mouth, nose, throat, eyes, and genitals).This conditioncan occur at any age, but often strikes people in middle or older age. "Due to its pivotal implication in the mechanisms of acantholysis in pemphigus, Pharmacologic inhibition of Stat3 through topical drugs may also hold promise in the field of targeted therapy in pemphigus." (PMID 31293582, 2019).
pericardial effusion (1 paper, 2022). Fluid collection within the pericardial sac, usually due to inflammation. "Neither the Stat3 inhibition by AG490 nor the Stat3 upregulation by LIF had significant effects in rescuing body length, eye size or pericardial effusion under hypoxia." (PMID 36051436, 2022).
peritoneal disease (1 paper, 2024). "Knockdown of IRAK1 impaired tumor growth in peritoneal disease models, and impaired HA-induced spheroid growth and STAT3 phosphorylation." (PMID 38796478, 2024).
plasmacytoma (1 paper, 2024). Plasmacytoma is a localized mass of neoplastic monoclonal plasma cells that represents approximately 5% of all plasma cell neoplasms. "In another study with mouse plasmacytomas, i.e., tumors of mature plasma cells, EEF1A2 knockdown expression decreased IL-6-mediated activation of STAT3 and AKT pathways, leading to a decrease in proliferation of plasmacytomas (PCT) cell lines with delayed cell-cycle entry." (PMID 38172654, 2024).
pleural mesothelioma (1 paper, 2025). A neoplasm that arises from the mesothelial cells of the pleura. "Consistently, MIA-602 and MIA-690 have been reported to suppress STAT3 activity in SCLC and NSCLC cell lines in vitro and in pleural mesothelioma in vivo by inhibiting NF-κB, COX-2, and MMPs, both alone and in combination with chemotherapy drugs." (PMID 40244089, 2025).
polyp (1 paper, 2022). A usually exophytic mass attached to the underlying tissue by a broad base or a thin stalk. "After AOM/DSS treatment, the polyp multiplicity and load of Htr2bΔIEC mice were increased compared with those of WT mice, but double knockout of Stat3 and Htr2b attenuated these increases to levels consistent with those of WT mice." (PMID 35664068, 2022).
posterior uveitis (1 paper, 2012). Inflammation of the choroid as well as the retina and vitreous body. "In this study, we have used ORLL-NIH001, a small synthetic compound that inhibits transcriptional activity of STAT3, to ameliorate EAU, an animal model of human posterior uveitis." (PMID 22238646, 2012).
primary progressive MS (1 paper, 2010). "STAT3 was reduced in primary progressive MS compared with healthy controls." (PMID 20405052, 2010).
progeria (1 paper, 2025). "To evaluate the status of STAT1 and STAT3 activation in the LmnaG609G/G609G mouse model, we performed western blot analyses on multiple tissues commonly affected by progeria." (PMID 40429989, 2025).
Pulmonary bulla (1 paper, 2025). Pulmonary bullae are rounded focal regions of emphysema with a thin wall which measure more than 1 cm in diameter. "Moreover, an unexpected finding in our study was the incidental discovery of a pulmonary bulla in a patient with a STAT3 mutation despite the absence of pulmonary infection." (PMID 40462219, 2025).
pulmonary edema (1 paper, 2020). Accumulation of fluid in the lung tissues causing disturbance of the gas exchange that may lead to respiratory failure. "Ginseng could reduce the pathologic damage, neutrophil aggregation, proinflammatory factors, and pulmonary edema in vivo and inhibit the PI3K-Akt signaling pathway and MAPK signaling pathway through downregulating expressions of STAT3, VEGFA, FGF2, PIK3CA, MAPK1, and IL2." (PMID 33746744, 2020).
radiation pneumonitis (1 paper, 2023). Inflammation of the lung due to harmful effects of ionizing or non-ionizing radiation. "In a mouse model, the protective effects of delayed treatment of WP1066 suggested that STAT3 signaling could be a therapeutic target for radiation pneumonitis." (PMID 37762522, 2023).
rapidly progressive glomerulonephritis (1 paper, 2025). Inflammation of the glomeruli that is characterized by a rapid loss in renal function with glomerular crescent formation observed on biopsy; it is often seen in patients with concomitant autoimmune disease, like Goodpasture's syndrome or systemic lupus erythematosus. "In 2017, researchers found that loss of KLF4, a zinc-finger transcription factor, along with dysregulated signal transducer and activator of transcription 3 (STAT3) signaling, enhances glomerular epithelial cell (GEC) proliferation in both rapidly progressive glomerulonephritis and FSGS." (PMID 40246828, 2025).
respiratory allergy (1 paper, 2020). "The current study highlights STAT3 and IRF4 as possible effectors of PM exposure and inform future functional analyses to reveal the biological and pathological background of PM caused respiratory allergy." (PMID 32448264, 2020).
retinal detachment (1 paper, 2017). An eye emergency condition which may lead to blindness if left untreated. "However, Western blot analysis of aqueous humor and vitreous samples showed an increase in IL6 downstream effectors, p-STAT3 (9.26 fold, p < 0.01) and p-Erk1/2 (3.84 fold, p < 0.01) after retinal detachment (RD1)." (PMID 28645275, 2017).
salivary gland disease (1 paper, 2020). "Another study found that in a co-culture of NOD mice salivary gland acinar cells (SGAC) and B-lymphocyte (an in-vitro model of salivary gland disease in SS), there was a significant increase in production of cytokines IL-6 and IL-1β by B-lymphocytes and increased phosphorylation of STAT3 in SGAC." (PMID 32849505, 2020).
SARS-CoV infection (1 paper, 2020). "On the other hand, SARS-CoV infection is known to de-phosphorylate STAT3 tyrosine 705 in epithelial cells." (PMID 33284859, 2020).
sciatic nerve lesions (1 paper, 2024). "To investigate potential interactions between CXCR4 signaling and STAT3 in the pro-regeneration state of cervical DRG neurons induced by unilateral sciatic nerve lesions, we administered AMD3100 intrathecally and analyzed the activation and nuclear translocation of STAT3." (PMID 39796050, 2024).
Senile plaques (1 paper, 2019). Senile plaques are extracellular deposits of amyloid in the gray matter of the brain. "In the neuronal compartment, the activation of STAT3 has been observed in senile plaques and it is involved in the neuronal loss by apoptosis in the brain." (PMID 30781690, 2019).
sickle cell disease (1 paper, 2024). Sickle cell anemias are chronic hemolytic diseases that may induce three types of acute accidents: severe anemia, severe bacterial infections, and ischemic vasoocclusive accidents (VOA) caused by sickle-shaped red blood cells obstructing small blood vessels and capillaries. "Benign indications for HSCT include sickle cell disease and genetic mutations leading to immunodeficiency diseases, i.e. GATA2, STAT3, DOCK8, PI3K gene mutations." (PMID 38756303, 2024).
skin changes (1 paper, 2022). "Exacerbated inflammatory skin changes in the HFD-fed Apoe−/− mice were confirmed by the increased expression of IL-23p19, signal transducer and activator of transcription-3 (STAT3), and phospho-STAT3 in the epidermis of inflamed skin, which are known to be activated in psoriatic skin." (PMID 35457132, 2022).
soft tissue tumors (1 paper, 2011). "Univariate logistic regression analysis: Significant association between expression of STAT3 and pSTAT3 and clinicopathological characteristics of soft tissue tumors." (PMID 21575192, 2011). "The purpose of this study was to investigate the expression levels of STAT3 and pSTAT3 in various soft tissue tumors and to associate it with its clinicopathological characteristics." (PMID 21575192, 2011). "Our data also indicates that increased activation of STAT3 could be associated with more aggressive biological behavior of soft tissue tumors." (PMID 21575192, 2011). "Our data suggests that STAT3 may be a key regulatory molecule in the malignant potential of soft tissue tumors and can be piloted as diagnostic marker in soft tissue tumors." (PMID 21575192, 2011). "Our data showed that constitutive activation of STAT3 in human soft tissue tumors is significantly associated with its clinicopathological parameters such as tumor grade, plane of the tumor, tumor size and tumor necrosis, which may possibly have potential diagnostic and prognostic implications." (PMID 21575192, 2011). "The percentages of positive nuclear expression of STAT3 and pSTAT3 in benign, intermediate, and malignant soft tissue tumors were also analyzed." (PMID 21575192, 2011). "Among the tumor samples, STAT3 mRNA was found to be overexpressed in malignant and intermediate tumors when compared with benign soft tissue tumors." (PMID 21575192, 2011). "In our study we examined the expression levels of STAT3 and pSTAT3 in different grades of soft tissue tumors and correlated with its clinicopathological characteristics." (PMID 21575192, 2011). "Immunohistochemical staining revealed both cytoplasmic and nuclear localization of STAT3 and pSTAT3 in benign, intermediate, and malignant soft tissue tumors." (PMID 21575192, 2011). "Of the 82 soft tissue tumor samples, fifty four (65.8%) showed immunoreactivity for STAT3 and twenty eight (34.1%) for pSTAT3." (PMID 21575192, 2011). "Considering the important role of STAT3 and pSTAT3 in various cancers, our study aimed to analyze the expression levels of STAT3 and pSTAT3 in soft tissue tumors by Immunohistochemistry, Western blotting and RT-PCR." (PMID 21575192, 2011). "Expression levels of STAT3 and pSTAT3 in benign, intermediate and malignant human soft tissue tumors." (PMID 21575192, 2011). "In addition we compared STAT3 and pSTAT3 expression with clinicopathologic parameters of soft tissue tumors." (PMID 21575192, 2011). "In the current study we observed a distinct pattern of STAT3 and pSTAT3 expression in soft tissue tumors, which differed significantly between benign, intermediate and malignant tumors and showed significant association with various histopathological parameters." (PMID 21575192, 2011). "However, whether constitutive STAT3 signaling plays a key role in the survival and growth of soft-tissue tumors is still unclear and hence needs to be elucidated further." (PMID 21575192, 2011).
sporotrichosis (1 paper, 2024). The commonest and least serious of the deep mycoses, characterized by nodular lesions of the cutaneous and subcutaneous tissues. "The results showed that the protein expressions of IL-6, JAK3, STAT3, and SOCS3, as well as phosphorylated JAK3 and STAT3, were significantly upregulated, suggesting that the JAK/STAT signaling pathway was activated during the occurrence and development of sporotrichosis." (PMID 38172590, 2024).
squamous cell carcinoma in situ (1 paper, 2007). "We only have one specimen in grade I that is negative, so the sample number is too small to draw conclusion for grade I. We also observed the elevation of Stat3 phosphorylation from Stage 0 to IIB and even detected two out of three squamous cell carcinoma in situ (TisN0M0) are positive." (PMID 17311011, 2007).
squamous intraepithelial lesions (1 paper, 2024). "STAT3 was implicated in the progression from HSIL to SCC in a report that also found that the upregulation of several genes involved in immune response and inflammation was crucial in the transformation from normal cervical cells to low-grade squamous intraepithelial lesions (LSIL)." (PMID 38891028, 2024).